HCN2 (hyperpolarization activated cyclic nucleotide gated potassium and sodium channel 2)
Description:
Hyperpolarization-activated ion channel that is permeable to sodium and potassium ions. Displays lower selectivity for K(+) over Na(+) ions. Contributes to the native pacemaker currents in heart (If) and in neurons (Ih). Can also transport ammonium in the distal nephron (By similarity). Involved in the initiation of neuropathic pain in sensory neurons (By similarity).
Synonyms: BCNG-2; BCNG2; HAC-1; EIG17; FEB2; GEFSP11
Tractability: Small molecule: a structure with a bound ligand is known; it belongs to a druggable protein family. Antibody: UniProt places it where antibodies can reach, with high confidence; its Gene Ontology location is reachable by antibodies, with high confidence; UniProt predicts a signal peptide or a membrane-spanning region. PROTAC: ubiquitination databases record sites on it; its protein half-life has been measured; a small molecule that binds it is known.
Target class: Ion channel; Voltage-gated ion channel; Cyclic nucleotide-regulated channel
Gene: Protein-coding gene on chromosome 19 (589,881 to 617,159, forward strand). Ensembl gene ENSG00000099822.
Subcellular location: Cell membrane
Pathways (Reactome):
Neuronal System: HCN channels
Gene Ontology:
Molecular function: identical protein binding; intracellularly cAMP-activated cation channel activity; protein binding; voltage-gated potassium channel activity; voltage-gated sodium channel activity; molecular adaptor activity; monoatomic ion channel activity; PDZ domain binding; protein-containing complex binding; sodium channel activity
Biological process: cellular response to cAMP; cellular response to cGMP; potassium ion import across plasma membrane; potassium ion transmembrane transport; regulation of membrane potential; sodium ion import across plasma membrane; sodium ion transmembrane transport; ammonium transmembrane transport; cell-cell signaling; membrane depolarization during cardiac muscle cell action potential; regulation of membrane depolarization; cellular response to aldosterone; monoatomic ion transport; potassium ion transport; response to hormone; response to xenobiotic stimulus; transmembrane transport
Cellular component: HCN channel complex; plasma membrane; axon; dendrite; voltage-gated potassium channel complex; dendrite membrane; dendritic shaft; membrane; neuronal cell body; somatodendritic compartment
Genetic constraint (gnomAD): Loss-of-function variants: 18 observed, 42.56 expected, observed/expected ratio (o/e) 0.42, 90% interval 0.29 to 0.63. The synonymous counts are far from expectation, so gnomAD's model fits this gene poorly and the ratio says little. Missense variants: 742 observed, 892.24 expected, observed/expected ratio (o/e) 0.83, 90% interval 0.78 to 0.88. Synonymous variants: 563 observed, 380.66 expected, observed/expected ratio (o/e) 1.48, 90% interval 1.38 to 1.59.
Gene-disease validity (ClinGen):
ClinGen rates the evidence that HCN2 causes each of these diseases.
complex neurodevelopmental disorder (autosomal dominant; autosomal recessive): Definitive. A disorder that involves more than one phenotype associated with the central nervous system, including but not limited to intellectual disability, autism, and seizures (epilepsy).
epilepsy (autosomal dominant): Limited. A brain disorder characterized by episodes of abnormally increased neuronal discharge resulting in transient episodes of sensory or motor neurological dysfunction, or psychic dysfunction.
Homologues: Orthologues: macaque HCN2 (99% identical), pig HCN2 (97% identical), dog HCN2 (97% identical), rat Hcn2 (92% identical), mouse Hcn2 (92% identical), guinea pig HCN2 (70% identical), tropical clawed frog HCN2 (70% identical), Drosophila melanogaster CngA (15% identical), Caenorhabditis elegans tax-4 (15% identical), Drosophila melanogaster CngB (14% identical), Drosophila melanogaster CG6026 (14% identical), Caenorhabditis elegans cng-2 (13% identical), and 2 more. Paralogues in human: HCN4 (64% identical), HCN1 (59% identical), HCN3 (53% identical), KCNH2 (20% identical), KCNH4 (19% identical), KCNH7 (19% identical), KCNH8 (18% identical), KCNH5 (18% identical), CNGA3 (18% identical), KCNH3 (18% identical), KCNH1 (18% identical), CNGB1 (17% identical), and 5 more.
Diseases named in the same sentence as HCN2 in open-access papers:
HCN2 is named in the same sentence as 89 diseases in open-access papers, as found by Europe PMC text mining. Sharing a sentence is not in itself a finding about the gene and the disease. The quoted sentences say what the papers report.
epilepsy (19 papers, 2012 to 2026). "Studies have demonstrated that abnormal HCN2 function is closely associated with epilepsy, especially absence epilepsy." (PMID 41603014, 2026). "Second, human genetic studies have identified rare variants of HCN2 in multiple epilepsy patients, involving two types of mechanisms: GOF and LOF." (PMID 41603014, 2026). "Only 2 individuals with HCN2 variants had ID: 1 of the 3 individuals from the family carrying the p.(Val246Met) variant, and 1 girl presenting ID and epilepsy, caused by a de novo p.(Gly460Asp) variant." (PMID 40468825, 2025). "Based on the electrophysiological studies on cell models, both GOF and LOF HCN2 variants are related to epilepsy." (PMID 35663267, 2022). "There is also evidence of a loss-of-function point mutation in HCN2 that contributes to generalized epilepsy in humans." (PMID 34768904, 2021). "As illustrated above, mouse models have proved important for studying epilepsy related to HCN2 mutations." (PMID 34768904, 2021). "In support of a role of HCN2 channels in epileptic seizures, a mutation in HCN2 was recently causally linked to general epilepsy." (PMID 24324597, 2013). "The bidirectional mechanisms of these variants indicate that either a decrease or an increase in HCN2 function alone may disrupt thalamocortical rhythms and trigger epilepsy." (PMID 41603014, 2026). "Indeed, the individuals carrying the p.(Met374Leu) HCN2 or the p.(Met305Leu) HCN1 variants have epilepsy and neurodevelopmental disorders." (PMID 40468825, 2025). "By describing 21 additional individuals with pathogenic HCN2 variants, we expand the phenotype of HCN2‐related disorders, from mild epilepsies with normal cognition, to phenotypes, including ID with or without epilepsy, individuals with DEE, and movement disorders." (PMID 40468825, 2025). "As proposed for the p.(Met305Leu) HCN1 variant, blocking the aberrant p.(Met374Leu) HCN2/HCN1 leaking channels could be a therapeutical strategy to prevent epilepsy." (PMID 40468825, 2025). "Besides, the loss of HCN2 channels on interneurons and thalamocortical relay neurons has been suggested as a possible underlying mechanism of epilepsy as shown in simulation study on a hippocampal CA1 pyramidal neuron synapse model and HCN2-null mouse." (PMID 35663267, 2022). "In this study, a screening in families with epilepsy identified a recessive point mutation in HCN2." (PMID 34768904, 2021). "Additionally, point mutations in the hcn2 gene were uncovered in patients suffering from febrile seizures or epilepsy." (PMID 34206649, 2021). "These functional data confirm that HCN2 expression stabilizes excitability, and that removal of HCN2 contribution in homozygous E515K variants is associated with increased excitability, a condition predisposing to epilepsy." (PMID 25805968, 2015). "GRM1 is associated with a number of neurological diseases including schizophrenia and depression and is significantly increased +1.83 fold, and HCN2, which contributes to spontaneous brain rhythmic activity, and dysfunction is associated with epilepsy, is increased +2.7 fold." (PMID 25183238, 2014). "It is now the 3rd HCN mutation found in seizures and epilepsy, all of which affect HCN2." (PMID 24324597, 2013). "In a more recent study based on HCN candidate-gene screening of a small cohort of patients (n = 113), our group characterized for the first time a loss-of-function HCN2 mutation that could be shown from functional studies to be directly involved in human epilepsy." (PMID 25805968, 2015). "Genetic variants in the HCN1, HCN2, and HCN4 have been identified in patients with various forms of epilepsy, including febrile seizures, temporal lobe epilepsy, absence epilepsy, and epileptic encephalopathy." (PMID 39361439, 2024). "HCN channels are composed of four subunits (HCN1‐4), with HCN1, HCN2, and HCN4 previously linked to epilepsy." (PMID 39361439, 2024).
epilepsy (continued). "In one study, global HCN2 deletion in mice resulted in signs of epilepsy, ataxia, and premature death; therefore, mice with selectively ablated HCN2 in nociceptive neurons expressing NaV1.8 were created to study its pathophysiology." (PMID 37893054, 2023). "Dendritic HCN1 and HCN2 channels were found to be downregulated in a pilocarpine model of epilepsy, while in the chronic period, expression of these channels increased." (PMID 37293624, 2023). "We identified pathogenic variants of HCN1 (n = 24), HCN2 (n = 8), HCN3 (n = 2), and HCN4 (n = 6) that were associated with epilepsy in 74 cases (43 HCN1, 20 HCN2, 2 HCN3, and 9 HCN4)." (PMID 35663267, 2022). "Pathogenic variants of HCN1, HCN2, HCN3, and HCN4 have been reported to be associated with epilepsy in 74 cases, and they have diverse phenotypes." (PMID 35663267, 2022). "The importance of HCN malfunction in epilepsy has also been highlighted by the identification of a deletion of three consecutive prolines in HCN2 in patients that have generalized epilepsy with febrile seizures." (PMID 34768904, 2021). "Studies of Ih and HCN channels in thalamocortical relay neurons of rat (WAG/Rij; GAERS) and mouse (HCN2-/- knock-out) models of Absence epilepsy." (PMID 26578877, 2015). "Furthermore, the evidence for variants in HCN1, HCN2, and HCN4 in human epilepsy has rapidly grown in recent years." (PMID 39361439, 2024). "Moreover, dysfunction in HCN channels, especially HCN1, HCN2, and HCN4 has been linked to multiple neurological and neurodegenerative disorders, including epilepsy, Alzheimer’s disease, Parkinson’s disease, and NP." (PMID 37893054, 2023). "Mutations in HCN2 and HCN3 can also contribute to epilepsy in some cases." (PMID 34149352, 2021). "As numerous ion channel blockers and openers are already approved for human use for arrhythmias, epilepsy, etc., future efforts at identifying novel and more specific HCN2 drugs may be warranted, as part of a strategy to identify useful electroceuticals." (PMID 32528251, 2020). "Therefore, we focused our validation on two ASMs: Hcn2 with known roles in epilepsy, inflammatory and chronic pain, and Park7 (or DJ-1) for Parkinson’s disease." (PMID 29387450, 2017). "In addition, our findings highlight the association of mono and biallelic HCN2 variants with ID with or without epilepsy." (PMID 40468825, 2025). "Seizures provoke a prolonged remodeling of HCN1 and HCN2 expression, supporting the presence of a transcriptional channelopathy involving HCN channels which contributes to the development of epilepsy." (PMID 25805968, 2015). "Our data highlight that the related HCN2 phenotype ranges from febrile seizures or mild epilepsy without ID to severe forms of epilepsy with ID and ID without epilepsy." (PMID 40468825, 2025). "Our findings broadened the HCN2 disease clinical spectrum to include DD/ID with or without epilepsy." (PMID 40468825, 2025). "In a pilocarpine-induced epilepsy model, dendritic HCN1 and HCN2 channels were initially downregulated but later increased during the chronic phase, indicating that regional Ih density may influence seizure susceptibility or resistance." (PMID 41318467, 2025). "Consistent with other mice lacking HCN2 expression, Trls2-/- mice showed persistent spike-wave discharges consistent with an absence epilepsy-like phenotype." (PMID 29466436, 2018).
idiopathic generalized epilepsy (10 papers, 2015 to 2025). A generalised epilepsy that encompasses several common seizure phenotypes including childhood absence epilepsy, juvenile absence epilepsy, juvenile myoclonic epilepsy and epilepsy with generalized tonic-clonic seizures alone. "A study of human subjects revealed a role for HCN2 in susceptibility to juvenile myoclonic epilepsy." (PMID 37293624, 2023). "A recent study found that photosensitivity contributes to generalized epilepsy in variants of gain-of-function heterozygous HCN2 patients." (PMID 34768904, 2021). "HCN2 loss-of-function instead causes spontaneous generalized epilepsy, both in genetically modified animals and in animals carrying a spontaneous truncating mutation." (PMID 30127718, 2018). "This phenotype is clearly milder than the pharmacoresistant generalized epilepsy with tonic-clonic seizures with autosomal recessive inheritance associated with the HCN2 mutation (E515K) we previously reported." (PMID 30127718, 2018). "Furthermore, human research has implicated HCN2 in juvenile myoclonic epilepsy, and HCN2 knockout animals exhibit spontaneous absence seizures and cardiac sinus arrhythmia." (PMID 41318467, 2025). "Most of the cases carrying HCN2 gene pathogenic variants can present clinically with either febrile seizures, or febrile seizure plus or genetic generalized epilepsy with febrile seizure plus or genetic or idiopathic generalized epilepsy." (PMID 35663267, 2022). "The HCN2 p.R527Q variant of unknown significance has been reported in one case that presented with idiopathic generalized epilepsy." (PMID 35663267, 2022). "For example, HCN1 and HCN2 functional gene variants that result in an alteration in the amino acids critical to conferring the electrophysiological characteristics of the channel are associated with idiopathic generalized epilepsy." (PMID 34768904, 2021). "Human studies suggest that HCN2 contributes to juvenile myoclonic epilepsy, and its prominent expression in the thalamus facilitates the spontaneous firing of thalamocortical neurons during oscillations and 3-Hz spike-and-wave patterns." (PMID 41318467, 2025). "This assumption may indeed apply since early infantile epileptic syndromes and idiopathic generalized epilepsy has been associated with mutations in HCN1 and HCN2 channel genes." (PMID 26578877, 2015). "HCN2 global KO models have not been tested for the studies of pain, since they are associated with severe neurological phenotypes, such as generalized epilepsy and ataxia, and are not prone to behavioral studies." (PMID 25805968, 2015). "Additionally, patients with FSs and GEFS+ persons have specific HCN2 channel mutations but not those with idiopathic generalized epilepsy, suggesting that HCN2 channels play a special role in attacks triggered by fevers." (PMID 36540525, 2022). "Further, specific HCN2 channel mutations have been found in association with febrile seizure and GEFS+ patients, but not idiopathic generalised epilepsy patients, implying a specific role for HCN2 channels in seizures precipitated by fevers." (PMID 35096712, 2021).
Anxiety (8 papers, 2018 to 2026). Intense feelings of nervousness, tension, or panic often arise in response to interpersonal stresses. "In our experiment, however, overexpressing HCN2 in the vCA1 affected the sensory dimension of pain but showed limited influence on anxiety-like behaviors and cognition in models of pain in mice." (PMID 37762124, 2023). "These neurobehavioral experimental results show that blocking HCN2 can aggravate sevoflurane exposure-induced cognitive impairment and anxiety-like behaviors, which presents a synergistic effect." (PMID 36104739, 2022). "Having demonstrated the effectiveness of HCN2 overexpression in enhancing Ih current, we next examined the effects of VTA HCN2 overexpression on depression- and anxiety-related behaviors in control and CMS-exposed mice." (PMID 29256865, 2018). "We have shown that CMS led to a decrease in Ih current in VTA dopamine neurons, while shRNA knockdown of HCN2 recapitulated the depression- and anxiety-like behavioral effects of CMS." (PMID 29256865, 2018). "Interestingly, the HCN4-KO has been shown to be reflected in thermal hypersensitivity and increased anxiety behavior, contrary to initial expectations based on the findings with HCN2-KO models." (PMID 37496803, 2023). "Accordingly, we deemed that sevoflurane leads to cognitive impairment, anxiety-like behaviors, and neuroinflammation of PND through regulating PEX5R/Trip8b-HCN2 channel interaction." (PMID 36104739, 2022). "Blocking HCN2 by ZD7288 treatment further activated microglia and aggravated sevoflurane exposure-induced anxiety-like behavior, cognitive impairment, and neuroinflammation." (PMID 36104739, 2022). "A knockdown of HCN2 by lentiviral shRNA-HCN2 shRNA in the VTA produced depressive- and anxiety-like behavior, and overexpression of HCN2 in the VTA prevented the development of CMS-induced depressive-like behavior." (PMID 31231190, 2019). "Taken together, these results indicate that shRNA knockdown of HCN2 in the VTA is sufficient to recapitulate the depressive- and anxiety-like behaviors seen following CMS exposure." (PMID 29256865, 2018). "We provide evidence that CMS led to a decrease in Ih current in NAc lateral shell-projecting VTA dopamine neurons, and that manipulating HCN2 expression in the VTA can powerfully regulate depressive- and anxiety-like behavior." (PMID 29256865, 2018). "Thus, HCN2 channels in the VTA play a critical role in regulating depressive- and anxiety-like behavior in both unstressed and chronically stressed mice." (PMID 29256865, 2018). "Having confirmed the effectiveness of shRNA knockdown of HCN2 in the VTA, we next determined whether HCN2 in the VTA regulates depressive- and anxiety-like behaviors." (PMID 29256865, 2018). "Furthermore, shRNA-mediated HCN2 knockdown in the VTA was sufficient to recapitulate CMS-induced depressive- and anxiety-like behavior in stress-naïve mice, whereas VTA HCN2 overexpression largely prevented CMS-induced behavioral deficits." (PMID 29256865, 2018). "To test whether overexpressing HCN2 affected other dimensions of chronic pain, we performed the elevated plus maze test (EPM) and the object–place recognition (OPR) tests to examine the anxiety and cognitive level, respectively." (PMID 37762124, 2023). "Additionally, HCN2 knockdown in the VTA was sufficient to induce depressive- and anxiety-like behavior in non-stressed mice, whereas HCN2 overexpression prevented the CMS-induced development of depressive-like behavior." (PMID 29256865, 2018). "Importantly, this decrease in Ih current is behaviorally relevant, as shRNA knockdown of HCN2 in the VTA was sufficient to recapitulate depressive- and anxiety-like behavior, while VTA HCN2 overexpression prevented the CMS-induced development of depressive-like behavior." (PMID 29256865, 2018). "Furthermore, we determined whether virus-mediated knockdown or overexpression of HCN2 in the VTA affects depression- and anxiety-like behaviors." (PMID 29256865, 2018).
Anxiety (continued). "Thus, the downregulation of HCN2 channels in VTA dopamine neurons may be a primary contributor to the CMS-induced development of depressive- and anxiety-like behaviors." (PMID 29256865, 2018).